TNF (tumor necrosis factor)
Diseases named in the same sentence as TNF in open-access papers (continued):
Sharing a sentence is not in itself a finding about the gene and the disease.
Hepatitis (continued). "D-limonene has also been reported to inhibit TNF-α and TGF-β1 mRNA expression and alleviate hepatitis in rats." (PMID 37375600, 2023). "In the group of children with hepatitis, there was a positive correlation between GGTP activity and children’s age (ρ = 0.242, p = 0.047), lymphocyte count (ρ = 0.418, p = 0.002), and TNF-α concentration (ρ = 0.324, p = 0.017)." (PMID 37834802, 2023). "The primary regulator in numerous experimental hepatic injury models, particularly CCl4-induced hepatitis, is iNOS, COX- 2, and TNF-α are the proinflammatory genes that are induced by an early increase in TNF-α levels." (PMID 37123086, 2023). "In our study of a group of EBV-infected children with hepatitis, we confirmed that an increased GGTP activity correlates with increased lymphocyte counts and TNF-α concentrations." (PMID 37834802, 2023). "We detected the transcription and translation of inflammatory factors such as IL-1β and TNF-α in the liver, and proved the inhibitory effect of GFL on BDL-induced hepatitis." (PMID 36278176, 2022). "In a previous study, adipose tissue-derived autologous MSCs-derived exosomes attenuated renal inflammation, decreased TNF-α, IL-6, and IL-1-β in the renal vein, and reduced the serum levels of TNF-α, IFN-γ, IL-6, IL-18, and IL-1β in a hepatitis model." (PMID 35279651, 2022). "In postpartum hepatitis flare group, activation of CD8+ T cells can produce TNF-α and IFN-α and induce postpartum hepatitis." (PMID 36685527, 2022). "Hepatitis is further aggravated, and HCC is further encouraged by the simultaneous production of TNF-α, IFN-γ, IL-12, IL-4, and IL-13." (PMID 36281288, 2022). "In the mouse model of concanavalin A (ConA)-induced hepatitis, which depends on activation of CD4+ T cells and NKT cells, TNF mediates liver damage independently of transcriptional inhibition." (PMID 35122118, 2022). "Recent research demonstrated the increased level of TNF-α, ILs, and IFN-γ in Con A-induced hepatitis." (PMID 36145841, 2022). "The mRNA expression of IL-1β, IL-6, TNF-α, TGF-β, α-SMA, Collagen I, Collagen IV, and Fibronectin in the CCl4 group were significantly increased compared with the control group, demonstrated liver inflammation and fibrosis." (PMID 35842576, 2022). "In postpartum hepatitis mother, CD4+ T cells secreted more IFN-γ, IL-21, IL-2, TNF-α, and secreted more pro-inflammatory/anti-inflammatory cytokines." (PMID 36685527, 2022). "The main mechanism of action by which IL-1β was triggered by ROS combined with TNF-α to activate NF-κB to induce FGL2 expression, which intensifies the progression of hepatitis." (PMID 35136014, 2022). "However, additionally, anti-TNF agents, considered to be highly immunosuppressive, are able to reduce immunological responses, as was shown in studies investigating vaccination efficiency after a single vaccination against hepatitis A and B in comparison to healthy controls." (PMID 35052849, 2022). "TNF-α plays a dichotomous role in HBV infection, which acts as a mediator of anti-HBV immunity and induces liver inflammation, and sustained liver inflammation leads to liver fibrosis." (PMID 34926586, 2021). "Of note, with the clinical application of anti-TNF-α therapy in inflammatory bowel and rheumatic diseases, CHB patients are faced with a challenge of reactivation of hepatitis (Lee YH." (PMID 34926586, 2021). "Selection of these biomarkers was made based on the literature data suggesting that TNF-α, IFN-γ, IL-6, and IL-10 are important mediators in the development of ConA-induced hepatitis, and activities of transaminases are reliable indicators of liver damage." (PMID 33919375, 2021). "An increase in the levels of TNF-α, IL-6, and IFN-γ has been shown to correlate with the disease severity in ConA-induced hepatitis." (PMID 33919375, 2021). "FasL-producing NKT cells stimulated by recMφ-secreted TNF-α function as the final effectors in α-GalCer hepatitis and CpG-ODN hepatitis, especially in mice fed a Western diet." (PMID 34297734, 2021).
Hepatitis (continued). "Our study demonstrated that APAP and ROX co-treatment significantly increased the expression levels of TNF-α, INF-γ, VCAM-1, CXCL-1, STAT-3, Nrf-2, GSTA, GCLC-1, HO-1 and NQO1, suggesting that APAP and ROX co-treatment can induce liver inflammation." (PMID 32132876, 2020). "In another study, a PDE inhibitor with a strong activity against PDE7A (IC50 = 9 nM) has been investigated in the ConA-induced hepatitis model and it decreased ALT activity and TNF-α levels." (PMID 31899535, 2020). "In immune-mediated liver injury such as Con A-induced hepatitis, pro-inflammatory cytokines such as IFN-γ and TNF-α produced by T and NKT cells play a crucial role in the development of the pathological changes observed in liver." (PMID 31780731, 2019). "In addition, WEC was reported to inhibit the elevation of circulating TNF-α and IL-6 levels and ameliorate various chronic inflammatory diseases in animal models, including cotton pellet-induced granuloma and carbon tetrachloride- and γ-irradiation-induced hepatitis." (PMID 31394768, 2019). "The levels of IL-6, TNF-α, and IL-1β in liver macerate supernatants were measured in order to evaluate the early DEN-induced liver inflammation." (PMID 31049358, 2019). "The pro-inflammatory markers IL-1α, IL-1β, IL-6, TNF, ICAM-1, and VCAM-1 were all significantly upregulated under both hepatitis models." (PMID 29445190, 2018). "Baicalein suppressed serum TNF-α, IFN-γ, hepatic infiltration of monocytes, and up-regulated the apoptosis of monocytes in the liver in concanavalin A (Con A)-induced hepatitis." (PMID 29922155, 2018). "The major cytokines involved in hepatitis development are tumor necrosis alpha (TNF-α), interferon gamma (IFN-γ), interleukin-2 (IL-2), and IL-6, of which TNF-α and IFN-γ are the dominant cytokines in irreversible biological damage." (PMID 27035150, 2016). "In addition, drug-induced hepatitis may mimic classical autoimmune hepatitis, as can be seen with autoimmune hepatitis induced by minocycline, alpha methyldopa, nitrofurantoin, and anti-TNF blocking agents." (PMID 27293922, 2016). "It has been reported that TNF-α and IFN-γ participate in various forms of liver damage, such as viral, toxic, and autoimmune hepatitis, and play an important role in ConA-induced hepatitis." (PMID 27524863, 2016). "A number of proinflammatory cytokines play key roles in the progression of hepatitis, such as IL-2, IFN-γ, and TNF-α." (PMID 25821351, 2015). "In the case of Concanavalin-A-induced hepatitis, the ROS produced by CD68+ Kupffer cells is the final effector, while the TNF produced by CD11b+ Kupffer cells/Mφ and NKT cells is needed to activate and increase the CD68+ Kupffer cells." (PMID 26333171, 2015). "Both CpG-ODN and α-GalCer-mediated hepatitis are TNF/FasL/Fas pathway-dependent, and the final effectors in these types of hepatitis are FasL-expressing NKT cells activated by the TNF produced by CD11b+ Kupffer cells/macrophages." (PMID 24667392, 2014). "Earlier studies demonstrated that TNF-α and IFN-γ played an essential role in the model of Con A-induced hepatitis." (PMID 24808635, 2014). "One previous study has shown that TNF-α and IFN-γ regulated the release of inflammatory cytokines in Con A-induced hepatitis, and IFN−/−TNF−/− mice were free from liver injury by Con A administration." (PMID 24808635, 2014). "TNF-α and IFN-γ are the first cytokines producedafter ConA injection, and are the most critical in inducing hepatitis as anti-TNFand anti-IFN-γ antibodies confer protection against the disease." (PMID 21483776, 2011). "The secretion of these cytokines exhibited a positive correlation among the HIV participants, which aligns with findings from other studies indicating a correlation between the cytokines TNF-α, IL-6, and IL-8 in PLWH coinfected with hepatitis, as well as in individuals with chronic hepatitis." (PMID 41219858, 2025).
Hepatitis (continued). "Moreover, cynaroside decreased the expression of IL-1β, IL-6 and TNF-α,and inhibited HMGB1 in cecal ligation and puncture-induced liver inflammation." (PMID 38835771, 2024). "Hepatitis B immune status is of particular importance in patients with IBD, as there are reports of reactivation of hepatitis B infection in patients starting anti-TNF therapy." (PMID 38675746, 2024). "The IL-1β/TNF-α/NF-κB pathway is activated during the inflammation initiation process, and HRP can downregulate its activation in a dose-dependent manner, implying that this pathway is involved in the initiation of hepatitis." (PMID 37833431, 2023). "To determine whether CD73 expression of ERCs plays a role in regulating cytokines in Con A-induced hepatitis, we detected the levels of IFN-γ and TNF-α in the livers and sera from different groups." (PMID 37775797, 2023). "Taken together, these results suggest macrophage Ninj1 does not play a crucial role in the pathogenesis of LPS/D‐gal‐induced hepatitis and that TNF‐α release by macrophages is not a primary factor of the phenotype of conventional Ninj1 KO mice." (PMID 36071453, 2022). "Furthermore, we detected pro-inflammatory cytokines TNF, IL-1β, IL-12p70, IFN-γ, IL-6, IL-2, and IL-17A corresponding with ConA-induced hepatitis and found that pro-inflammatory factors all rise at 6 h after ConA injection." (PMID 36248904, 2022). "Additionally, compound 34 strongly reduced serum concentrations of TNFα, IFNγ, and IL-4, and diminished serum ALT and AST activities in ConA-induced hepatitis in mice." (PMID 35631676, 2022). "DIO mice expressed higher TNF-α and IL-1β levels in the adipose tissue after 24 weeks and in the liver after 40 weeks of consuming DIO, indicating that IR was established before the development of liver inflammation." (PMID 35889863, 2022). "Common side effects of anti-TNF therapy (used commonly in AS) include respiratory tract infections and hepatitis,5which are never evident preoperatively." (PMID 36539119, 2022). "Activation of STING was associated with an aggravated expression of several inflammatory cytokines, including IL-18, IL-6, IL-1β, TNFα, and C-X-C motif chemokine ligand 10 (CXCL-10) in HFD-induced NAFLD mice, whereas repressing STING signaling attenuated lipid accumulation and liver inflammation." (PMID 33924165, 2021). "Elevated levels of cytokines, including TNF-α, IL-lβ, IL-6, and chemokine monocyte chemoattractant protein-1 (MCP-1) after BDE-47 exposure, induced liver inflammation in mice, aggravated hepatic steatosis and fibrosis in the mouse by oxidative stress and increased pro-inflammatory cytokines." (PMID 33924165, 2021). "Recent studies reported that Vδ2+ γδT cells from patients with chronic HBV-infection with hepatitis flares responded less to IFNγ/TNF than those without hepatitis flares." (PMID 34360777, 2021). "Accordingly, IFNγ/TNF responses in Vδ2+γδT-cells were weaker in patients with CHB with hepatitis flare compared to those without hepatitis flares, and this functional deficit persisted beyond clinical resolution of CHB flare." (PMID 30998783, 2019). "Further, IFNγ/TNF responses were weaker in Vδ2+ γδT cells from chronic HBV infected patients with hepatitis flare when compared to those without hepatitis flare." (PMID 31507621, 2019). "Finally, our data suggest that the increased expression of Gal-3 in MCMV-infected livers protects hepatocytes from TNF-α facilitated apoptosis and necroptosis, and consequentially attenuates liver damage in MCMV-induced hepatitis." (PMID 30800112, 2019). "To test this mechanistic hypothesis in the hepatitis model induced by a viral pattern, we administered ETA, a decoy receptor of TNF-α, 1 h prior poly I:C injection." (PMID 30622241, 2019). "It has been shown that the alleviation of Con A-induced hepatitis was observed in IFN-γ−/− mice but not in TNF-α−/− mice, suggesting that IFN-γ rather than TNF-α is a key regulator in Con A-induced liver injury." (PMID 30177931, 2018).
Hepatitis (continued). "Although liver inflammation has been shown to drive hepatocarcinogenesis via TNF in DEN-induced and CCl4-induced murine models of hepatitis, TNF’s downstream target(s) that promote tumorigenic change in hepatocytes remain largely unknown." (PMID 29445190, 2018). "However, the levels of TNF-α (P < 0.05), IL-1β (P < 0.01), and particularly IFN-γ (6.55-fold increase, P < 0.01) were significantly increased in the serum of mice with hepatitis." (PMID 29695839, 2018). "In this model, however, LPS-induced lethality has been shown to be triggered by a caspase-dependent fulminant apoptotic hepatitis induced by TNF-α overproduction and not directly from the systemic inflammatory response." (PMID 28659918, 2017). "In this study, we found that pretreatment with DH extract significantly ameliorated liver injury and suppressed the production of inflammatory cytokines, including tumor necrosis factor (TNF-α) and interferon-γ (IFN-γ) in Concanavalin A- (ConA-) induced hepatitis (CIH)." (PMID 27524863, 2016). "We show that delivery of miR-511 to mice down-regulates TNFR1 protein and protects against TNF, as well as against endotoxic shock and lethal hepatitis, and that anti-miR-511 up-regulates TNFR1 and sensitizes for TNF, both in B and in S mice, breaking the resistance of S mice to TNF." (PMID 25995337, 2015). "Then, astaxanthin could provide protection against hepatitis by reducing the production of ROS and NO and reducing the activity of inducible nitric oxide synthase to inhibit cyclooxygenase (COX) and TNF-α levels." (PMID 25761053, 2015). "For example, in a mouse model that mimicked chronic parenteral nutrition use and intestinal injury, liver inflammation was correlated with higher levels of LPS in the portal vein and increased transcription of pro-inflammatory cytokines (IL6, TNF-alpha and TGF-beta) in Kupffer cells." (PMID 24465786, 2014). "TNF-α, IFN-γ, and IL-4 produced by macrophages, regulatory T cells, and natural killer T (NKT) cells play important roles in the development of the Con A induced hepatitis." (PMID 25126542, 2014). "The greater expression of TNF-alpha was mainly induced by leptospiral LPS, which indicated that TNF-alpha up-regulation may be related to severe hepatitis during leptospirosis." (PMID 24130911, 2013). "Furthermore, pretreatment with anti–IFN-γ or anti–TNF-α monoclonal antibodies (mAbs), or IFN-γ gene ablation confers protection against Con A-induced hepatitis, indicating that Th1-dependent cytokines are also involved." (PMID 23118999, 2012). "Con A-induced hepatitis is accompanied by an increase in the serum concentration of several proinflammatory cytokines, including tumor necrosis factor-α (TNF-α), interleukin-6 (IL-6), interferon-γ (IFN-γ) and interleukin-1 (IL-1) which contribute to the development of hepatitis." (PMID 23118999, 2012). "Patients 2 and 3 were treated with IL1RA without prior methotrexate or TNFα-inhibiting therapies, and both patients had received treatment with high-dose IV corticosteroids in the month preceding hepatitis." (PMID 20028520, 2009). "Of significance to the present study is that the levels of many cytokines (including IL-18, IFNs, TNF-α, IL-4 and TGF-β1) are elevated during hepatitis progression, and have been demonstrated to exhibit antiviral activity in both transgenic mice and cell culture systems." (PMID 19374779, 2009). "IL-6 has been shown to have a suppressive effect on TNFα and IL-1β production in peripheral blood mononuclear cells and exerts its anti-inflammatory effects in hepatitis by reducing the production of TNF." (PMID 19014513, 2008). "The same dose of TNF inhibitor was effective in suppressing liver inflammation induced by concavalin A administration, a model of hepatitis dependent on TNF production (data not shown)." (PMID 17352828, 2007).
Hepatitis (continued). "In addition, in one mouse model of MASLD, SB reduced hepatitis activity according to the NAS scale, production in the liver of TNF-α, IL-1β, interferon-γ, and IL-10 as well as the inflammatory cell chemoattractant CCL-2 and macrophage (Kupffer cells) biomarker F4/80." (PMID 39203520, 2024). "Notably, hepatitis induced by alpha-GalCer is mediated by tumor necrosis factor-α secreted by NKT cells and not by Kupffer cells." (PMID 38330036, 2024). "In our study, we confirmed that in the group of EBV-infected children without hepatological complications as well as those with hepatitis and concomitant biliary pole damage, the levels of IL-6 and TNF-α were significantly higher than in patients not infected with EBV." (PMID 37834802, 2023). "These chemically induced models alter multiple genes and pathways (PI3K-Akt, TNF, JAK-STAT, MAPK, Chemokine, NF-kappa B, TGF-beta signaling pathways, Apoptosis, and Cell cycle) and result in the development of hepatitis, which may be similar to that of HBV-induced hepatitis." (PMID 37446321, 2023). "The gradient changes in IL-1β, TNF-α, NF-κB, cAMP, PKA, CREB, and CYP2D6 during the inflammatory process, along with the occurrence and remission of inflammation, suggest that IL-1β may be involved in the pathological process of hepatitis." (PMID 37833431, 2023). "Although the TNF signalling pathway has been depicted as not critical for chronic exposure to CCl4, the cytokine is believed to contribute to the damage occurring in acute CCl4-induced hepatitis." (PMID 35806372, 2022). "The mechanism of EBV hepatitis is thought to be that EBV infected and activated CD8 + T-cells accumulate in the liver and the products of the EBV-infected CD8 + T cells or infiltrating cytotoxic T lymphocytes were interferon-γ, tumor necrosis factor and Fas ligand, which can destroy hepatocytes." (PMID 35189820, 2022). "The production of mouse serum pro-inflammatory cytokines tumor necrosis factor-α (TNF-α) and interferon-γ (IFN-γ), indicates that CGA restricts the infiltration of white blood cells and the production of pro-inflammatory cytokines to inhibit the occurrence of hepatitis." (PMID 35845802, 2022). "Firstly, serum GLB and hepatic TNF-α levels had weak positive correlations with hepatic emodin, TSG, EMG, and physcion exposure levels, suggesting that these four components of PM may induce liver inflammation." (PMID 36304159, 2022). "The time courses of four inflammatory mediators, namely IFN-γ, IL-6, IL-10, and TNF-α and the activities of both transaminases, i.e., ALT and AST, in the mice serum were modeled using the newly designed PK/PD/disease progression model of GRMS-55 in ConA-induced hepatitis in mice." (PMID 33919375, 2021). "Besides LPS-induced peritonitis, similar results were obtained in the ConA-induced hepatitis model, where the treatment with GPI, 6AN or clodronate liposomes inhibited inflammatory cytokines (TNF and IL-6), reduced liver damage, and decreased the mortality rate." (PMID 32286295, 2020). "In the cytokine profile generated for severe hepatitis (AST/AST > 400 U/L), we observed that in addition to IL-8 being significantly elevated during the acute phase (P = 0.00) and at defervescence (P = 0.01), TNFα was significantly elevated during the acute phase (P = 0.01)." (PMID 32124729, 2020). "Given the inverse associations between serum ALT and early IFNγ/TNF responses in γδT-cells to PMA/Ionomycin stimulation in CHB, CHB subjects with and without a recent hepatitis flare (ALT/ULN ≥10 within a month of immune analyses) were further compared for IFNγ/TNF responses in γδT-cells." (PMID 30998783, 2019). "TFA-JHDN-5 immunizations induced significantly more hepatitis, serum levels of TFA antibodies, CYP2E1 autoantibodies, and hepatic tissue levels of interleukin (IL)-1β, IL-2, IL-4, IL-5, IL-6, IL-17, interferon (IFN)-γ, and tumor necrosis factor (TNF)-α by 3 weeks." (PMID 30305319, 2018).